ZBTB6 (zinc finger and BTB domain containing 6)
Description:
May be involved in transcriptional regulation.
Synonyms: ZID; ZNF482
Tractability: PROTAC: ubiquitination databases record sites on it.
Gene: Protein-coding gene on chromosome 9 (122,908,053 to 122,913,323, reverse strand). Ensembl gene ENSG00000186130.
Subcellular location: Nucleus
Subcellular location (Human Protein Atlas): Nucleoplasm; Mitochondria
Gene Ontology:
Molecular function: protein binding; DNA binding; DNA-binding transcription repressor activity, RNA polymerase II-specific; RNA polymerase II cis-regulatory region sequence-specific DNA binding
Biological process: negative regulation of transcription by RNA polymerase II; regulation of cytokine production; regulation of immune system process
Cellular component: nucleoplasm; nucleus
Genetic constraint (gnomAD): Loss-of-function variants: 11 observed, 32.13 expected, observed/expected ratio (o/e) 0.34, 90% interval 0.21 to 0.57. The upper end of that interval is the gene's LOEUF score, 0.57, which puts it in group 2 of 6, group 1 being the genes least tolerant of losing a copy. Missense variants: 380 observed, 514.76 expected, observed/expected ratio (o/e) 0.74, 90% interval 0.68 to 0.8. Synonymous variants: 174 observed, 183.56 expected, observed/expected ratio (o/e) 0.95, 90% interval 0.84 to 1.08.
Homologues: Orthologues: chimpanzee ZBTB6 (100% identical), macaque ZBTB6 (99% identical), dog ZBTB6 (96% identical), guinea pig ZBTB6 (94% identical), pig ZBTB6 (94% identical), mouse Zbtb6 (92% identical), rat Zbtb6 (90% identical), tropical clawed frog zbtb6 (66% identical). Paralogues in human: ZBTB26 (43% identical), ZBTB12 (31% identical), BCL6 (23% identical), BCL6B (19% identical), ZBTB14 (17% identical), ZBTB46 (17% identical), ZBTB21 (17% identical), ZBTB49 (17% identical), ZBTB33 (16% identical), ZBTB7B (15% identical), NACC2 (15% identical), PRDM13 (15% identical), and 16 more.
Diseases named in the same sentence as ZBTB6 in open-access papers:
ZBTB6 is named in the same sentence as 6 diseases in open-access papers, as found by Europe PMC text mining. Sharing a sentence is not in itself a finding about the gene and the disease. The quoted sentences say what the papers report.
Crohn disease (1 paper, 2023). A gastrointestinal disorder characterized by chronic inflammation involving all layers of the intestinal wall, noncaseating granulomas affecting the intestinal wall and regional lymph nodes, and transmural fibrosis. "Although not reported in malaria, human ZBTB6 was one of the most differentially expressed genes in the whole blood of patients with Crohn’s disease." (PMID 37704951, 2023).
esophageal cancer (1 paper, 2023). A primary or metastatic malignant neoplasm involving the esophagus. "constructed a prognostic map for esophageal cancer, utilizing eight genes, including CDCA4, UBE2Z, AMTN, AK1, TLE1, FXN, ZBTB6, and APLN." (PMID 38098487, 2023).
glioma (1 paper, 2021). A benign or malignant brain and spinal cord tumor that arises from glial cells (astrocytes, oligodendrocytes, ependymal cells). "We detected TF binding sites for E2F1, HMX1, PAX5, REST and ZBTB6 in the promoters of DEGs present within the top six ‘glioma TADs’." (PMID 34341417, 2021).
tumor (1 paper, 2024). "Specifically, among the DHA up-regulated genes, we found ZBTB6 that significantly suppressed migration, invasion, and proliferation in GBM, as well as DAXX involved in the suppression of tumor growth and increase of GBM patients’ survival." (PMID 38429759, 2024).
ZBTB6 also shares sentences with these, for which no sentence is quoted: malaria (1 paper); type 2 diabetes (1).